HGF (hepatocyte growth factor)
Diseases named in the same sentence as HGF in open-access papers (continued):
Sharing a sentence is not in itself a finding about the gene and the disease.
tumor (continued). "CAFs and TAMs contribute to tumor growth and angiogenesis by releasing TGF-β, HGF, and VEGF, thereby fostering an immunosuppressive microenvironment." (PMID 41333481, 2025). "Among these, iCAFs have been shown to promote tumor progression through direct HGF secretion, mediating CAF-tumor cell interactions." (PMID 41408647, 2025). "Their activation within the TME is driven by tumor-secreted factors such as transforming growth factor-β (TGF-β), platelet-derived growth factor (PDGF), hepatocyte growth factor (HGF), and epidermal growth factor (EGF)." (PMID 40649958, 2025). "By using a specific MET tyrosine kinase inhibitor in a humanised hepatocyte growth factor (HGF) mouse model, we also establish that MET activity is required for ETV1/ERG‐mediated tumour growth." (PMID 39374163, 2025). "In this study, expression levels of key apoptotic and survival-related genes, including Bax, Bcl-2, Caspase-3, c-MET, and HGF in response to TAS-115 and its combination with DOXO in 3D tumor spheroids." (PMID 41289612, 2025). "CD74, HGF, and SUB1 are frequently overexpressed in NSCLC, promoting tumor proliferation and survival." (PMID 40136480, 2025). "RNA-seq data analysis highlighted the role of the HGF gene in LUAD diagnosis, demonstrating its strong correlation with patient prognosis and immune cell infiltration within the tumor microenvironment." (PMID 40136462, 2025). "It facilitates endothelial cell migration induced by VEGF, enhances tumor cell migration and proliferation through autocrine signaling involving Semaphorin 3A (Sema 3A) and HGF/scatter factor signaling pathways." (PMID 40430075, 2025). "Factors within the TME, like hepatocyte growth factor (HGF), which binds to the c-MET tyrosine kinase receptor activating β-catenin-dependent transcription, support CSC phenotypes and contribute to tumor heterogeneity by providing suitable niches for CSCs." (PMID 39578849, 2024). "Hyperactive signals sent primarily by tumour cells were identified, such as MDK, HGF, chemerin, and GDF15 signalling." (PMID 38318640, 2024). "Here, the authors show that co-activation of HGF/MET and Wnt/β-catenin signaling in mouse prostates results in DNPC-like tumor lesions with elevated expression of XPO1 and ribosomal proteins." (PMID 38336745, 2024). "One example of the use of DARPins for immuno‐oncology purposes is that of MP0250, a drug candidate that binds and inhibits vascular endothelial growth factor (VEGF) and hepatocyte growth factor (HGF), thus altering the tumor microenvironment." (PMID 39465903, 2024). "For instance, CAFs, a prevalent component of stromal cells in numerous cancers, secrete growth factors such as fibroblast growth factor (FGF) and hepatocyte growth factor (HGF), which are known to facilitate tumor growth and resistance to therapies." (PMID 39600368, 2024). "Tumor microenvironment (TME) factors, like hepatocyte growth factor (HGF) and periostin, enhance Wnt activity, sustaining tahe cancer stem cell phenotype." (PMID 39335624, 2024). "Research has shown that stromal-derived HGF acts as a mediator of resistance to VEGFR TKIs, resulting in increased tortuosity and disorganization of the tumor vasculature." (PMID 39201787, 2024). "They support tumour cell survival in the peritoneal fluid by secreting epidermal growth factor (EGF) and hepatocyte growth factor (HGF)." (PMID 38783165, 2024). "CAFs secrete factors such as TGF-β, hepatocyte growth factor (HGF), stromal cell-derived factor 1 (SDF-1), and IL-1β to mediate immune suppression, extracellular matrix remodelling, maintenance of tumor stemness, angiogenesis, and chemoresistance." (PMID 39273339, 2024). "By altering the composition and function of immune cells in the TME, HGF/c-MET signaling can inhibit the anti-tumor immune response, allowing tumor cells to evade immune system attacks." (PMID 39201787, 2024).
tumor (continued). "Examination of the CCC TME revealed activation of several signalling pathways (HGF, ANGPTL4, HBEGF, and FGF) that promote tumour growth and angiogenesis." (PMID 39149248, 2024). "Pro-tumor neutrophils secreted a variety of cytokines to sustain tumor growth, including epidermal growth factor (EGF), hepatocyte growth factor (HGF), and platelet-derived growth factor (PDGF)." (PMID 39061147, 2024). "CAFs also secrete pro-angiogenic factors such as VEGF, hepatocyte growth factors (HGF), and fibroblast growth factors (FGF), which contribute to tumor neovascularization." (PMID 39361163, 2024). "Upon activation, CAFs can release a range of soluble factors that can enhance tumor invasion and metastasis, such as TGF-β, hepatocyte growth factor (HGF), epidermal growth factor (EGF), FGF and IL-6 cytokine." (PMID 39139454, 2024). "HGF and its receptor c‐MET are known to shape the hepatic microenvironment and promote tumor growth in liver tumors." (PMID 39359691, 2024). "Previous studies showed that combination therapy using HGF and VEGF inhibitors effectively suppressed tumor angiogenesis." (PMID 39302921, 2024). "Cancer-associated fibroblasts and mesenchymal stromal cells produce hepatocyte growth factor (HGF), activating c-MET signaling in tumor cells and myeloid-derived suppressor cells (MDSC)." (PMID 39664377, 2024). "Binding of c-Met to its ligand, hepatocyte growth factor (HGF), triggers pathways that promote tumor growth." (PMID 39272847, 2024). "Studies have demonstrated that LC3C-mediated autophagy selectively governs migration and invasion of tumor cells stimulated by Met tyrosine kinase (RTK) and hepatocyte growth factor (HGF)." (PMID 39669571, 2024). "To understand the regulatory role of HGF/MET and Wnt/β-catenin signaling pathways in promoting DNPC-like tumor development, we assessed the transcriptomics of PCa cells from TripleTg mice." (PMID 38336745, 2024). "In instances of HGF-dependent c-MET activation, emibetuzumab obstructs HGF binding to c-MET, inhibiting c-MET phosphorylation and subsequent tumor growth suppression in both in vitro and in vivo settings." (PMID 39664377, 2024). "HGF, a hepatocyte growth factor, was confirmed to be upregulated in AML samples and cells and to promote the tumor malignancy of AML cells through targeted binding with miR-204." (PMID 39300580, 2024). "The HGF/c-MET pathway also regulates epithelial–mesenchymal transition (EMT) in NSCLC, an important process that enhances tumor cell migration and invasion, and serves as an adaptive drug resistance mechanism." (PMID 39201787, 2024). "The intercellular communication network in CM was found to be orchestrated primarily by tumour cells, and hyperactive signals sent primarily by tumour cells were identified, such as MDK, HGF, chemerin and GDF15 signalling." (PMID 38318640, 2024). "The interaction between stromal HGF and MET-expressing cancer cells plays a crucial role in tumor development within the tumor microenvironment (TME)." (PMID 39598385, 2024). "This hypoxic microenvironment triggers alternative pro-angiogenesis molecular pathways in tumor or stromal cells within the tumor microenvironment, including FGF-2, HGF, DLL4/Notch, CCL28, and others." (PMID 39075504, 2024). "MET’s interaction with its ligand, hepatocyte growth factor/scatter factor (HGF/SF), is particularly critical in promoting the epithelial to mesenchymal transition (EMT), which enhances tumor cell proliferation, motility, and anchorage-independent growth." (PMID 39449330, 2024). "For instance, fibroblasts and endothelial cells enhance glycolysis and lipid metabolism through secreted factors like TGF‐β, HGF, and vascular endothelial growth factor (VEGF), promoting tumor angiogenesis and nutrient supply." (PMID 39494561, 2024).
tumor (continued). "The expression of secreted protein‐coding genes, including MDK, HGF, RARRES2, GDF15, IL6 and MIA, was concentrated in the tumour cell‐enriched region, thus confirming the expression specificity of these signalling molecules." (PMID 38318640, 2024). "Cytokines like HGF, OPN, and SDF-1 secreted in the tumor microenvironment increased CD44v6 expression in CSCs and activated the Wnt/β-catenin pathway, which promoted migration and metastasis." (PMID 38672650, 2024). "HGF/Met signaling also increases lactic acid secretion via glycolysis, inhibiting human CTL proliferation and activity, and triggering tumor recurrence and metastasis." (PMID 39170944, 2024). "Activation of the HGF/Met axis has been extensively documented to stimulate cell proliferation, migration, invasion, and angiogenesis in HNSCC and other tumor types." (PMID 39469621, 2024). "The HGF/Met signaling pathway not only plays a role in modulating immune infiltration within the TME, but also impacts tumor cells in evading the anti-tumor immune response." (PMID 39201787, 2024). "The upregulation of RTKs such as HER3, HGF/c-MET, AXL, and FGFR enhances the PI3K/AKT/mTOR anx Src pathways, promoting tumor cell proliferation." (PMID 39769140, 2024). "These M2 TAMs secrete HGF, thereby activating the HGF/MET/ERK and PI3K/AKT pathways in the tumor cells and thus facilitating sorafenib resistance." (PMID 39682130, 2024). "Since hepatocyte growth factor (HGF) is the sole ligand for MET and is enriched in the tumor microenvironment, we first evaluated the function of MET on phosphorylating and activating STAT5A with the treatment of HGF in both LNCaP and C42B cells." (PMID 38745318, 2024). "Consistent with the results of single‐cell data, MDK signalling, HGF signalling, chemerin signalling, and GDF15 signalling were also observed to be hyperactive signals primarily sent by the tumour cells based on the ST data." (PMID 38318640, 2024). "ASCs are a source of several molecules that are thought to promote tumor development such as IGF-1, transforming growth factor beta 1 (TGFβ1), vascular endothelial growth factor (VEGF), hepatocyte growth factor (HGF), and IL-8." (PMID 38159164, 2024). "GASCs are likely to actively interact with tumor cells being involved in the accelerated tumor spreading by releasing VEGF and especially hepatocyte growth factor (HGF)." (PMID 39539752, 2024). "B cells isolated from GB patient samples have been shown to promote tumor cell proliferation and migration through the secretion of growth factors such as insulin-like growth factor-1 (IGF-1) and hepatocyte growth factor (HGF)." (PMID 38523646, 2024). "PMN-MDSCs were attracted to the tumor site, and upon entering, they generated transforming growth factor-beta (TGF-β) and hepatocyte growth factor (HGF)." (PMID 38361941, 2024). "Fibroblast clones secrete IL-6, IL-8, NFkB, IFN-y, HGF, CTGF, CCL5, and PGE5 to promote tumour growth." (PMID 39046819, 2024). "When activated by ligand hepatocyte growth factor (HGF), MET+ neutrophils release nitric oxide (NO) to limit tumor growth and metastasis." (PMID 38760815, 2024). "Hepatocyte growth factor (HGF) is another critical pleiotropic cytokine involved in numerous complex biological processes in tissue regeneration, tumour growth, and angiogenesis." (PMID 38792973, 2024). "Comparing changes in absolute cytokine levels for IFNγ and the IFNγ-inducible cytokines CXCL9 and CXCL10 to the tumor-related cytokines EGF, HGF and VEGF highlights the strong treatment related effects for IFNγ-pathway related cytokines." (PMID 38454126, 2024). "In some cancers, FN expression can act as a tumor suppressor, as observed in tyrosine kinase receptor Met and its ligand, hepatocyte growth factor (HGF)/scatter factor-mediated tumorigenesis." (PMID 38660622, 2024). "Based on these findings, 11 pairs of tumor and adjacent tissues before RFA and after RFA were collected for assessing mRNA expression of APC, FAS, HGF, PCNA and EFCAB7." (PMID 39276379, 2024).
tumor (continued). "Hepatocyte growth factor(HGF) induces the expression of SNAIL to activate EMT, invasion, andeventually tumor metastasis." (PMID 38967485, 2024). "Nanobody-based targeting of tumor ligands, including EGF, HGF, and VEGF, has resulted in efficient inhibition of tumor growth and metastasis." (PMID 36761751, 2023). "CAFs stimulate tumor angiogenesis and tumor cell proliferation by secreting growth factors (VEGF, HGF) and support tumor cell metabolism." (PMID 38139365, 2023). "It is also known that PI3K-AKT-mTOR signaling pathway activation via CAF-derived secretion, such as through CXCL12, VCAM1, IL-22, CXCL5, HGF, and SPARC, induces tumor proliferation, migration, and stemness." (PMID 37264057, 2023). "Disruption of growth factor signaling was an approach taken in one study, where antisense oligonucleotides targeting HGF, which was secreted by CAFs, inhibited VEGF production and CAF-induced increase in clonogenic potential in co-cultured tumor cells." (PMID 37046676, 2023). "Myofibroblast-secreted factors, specifically hepatocyte growth factor (HGF), activate beta-catenin-dependent transcription and subsequently restore the cancer stem cell phenotype in more differentiated tumor cells both in vitro and in vivo." (PMID 36600243, 2023). "MSCs are able to deliver a variety of cytokines and growth factors to the tumor site that were identified as anti-tumor agents, comprising IFN-α, IFN-β, IFN-γ, IL-2, IL-7, IL-12, IL-15, IL-18, IL-25, and NK4, an antagonist of HGF." (PMID 37686315, 2023). "TAMs express and secrete numerous factors that promote tumor growth, such as EGF (Epithelial Growth Factor), PDGF (Platelet-Derived Growth Factor), FGF (Fibroblast Growth Factor) or HGF (Hepatocyte Growth Factor)." (PMID 37143666, 2023). "For example, CAFs can produce hepatocyte growth factor (HGF), which further activates its cognate receptor, c-Met, on tumor cells resulting in a pro-tumorigenic environment by triggering invasive and metastatic behavior of tumor cells." (PMID 37607999, 2023). "We found that HGF (produced by fibroblasts) induced entrectinib resistance in tumor cells with NTRK1 or ROS1 rearrangement and that HGF‐induced resistance was reversed by combination with HGF/MET inhibitors." (PMID 36416133, 2023). "The HGF and MET genes are expressed in human glioma and medulloblastoma, where their increased relative abundance frequently correlates with tumor grade, tumor blood vessel density and poor prognosis." (PMID 36672409, 2023). "Rilotumumab (AMG102) is a fully human neutralizing monoclonal antibody against HGF that potently inhibited the growth of GBM-derived cell lines such as U87 MG, which has HGF/Met autocrine signaling, in culture and in tumor xenografts as a single agent." (PMID 36672409, 2023). "For example, miR-144/miR-451a, a tumor suppressor in HCC cells, can target HGF and MIF in HCC cells and induce M1 polarization and anti-tumor activity of TAMs via paracrine pathway." (PMID 37274242, 2023). "The main groups of Mabs in SCC therapy are Mabs targeting EGFR, HER2, HGF, and VEGF, alongside checkpoint inhibitors (including Mabs to PD‐1, CTLA4, and NKG2A) and tumor targeting Mabs." (PMID 37042307, 2023). "At present, numerous studies have demonstrated that HGF can regulate the expression of VEGF and promote tumor angiogenesis through its receptor c-Met." (PMID 36959792, 2023). "Interrogation for markers of c-Met pathway activation included analysis of HGF, c-Met, p-Met, p-ERK, p-Akt, and p-S6K expression by immunohistochemistry (IHC) in tumor cells." (PMID 36807743, 2023). "HGF is abundantly expressed in a critical TME component known as CAFs, while its receptor, c-MET, is highly expressed in tumor cells." (PMID 37919751, 2023). "Interactions between CAFs and cancer cells activate the HGF/MET signaling pathway, leading to tumor growth and metastasis." (PMID 37887325, 2023).
tumor (continued). "In activated hepatic stellate cells, HDAC7 localised to the cytoplasm through an interaction with the tumour‐suppressor cylindromatosis (CYLD), thus derepressing hepatocyte growth factor (HGF) expression." (PMID 35303381, 2023). "Meanwhile, tumorigenic markers, including HGF and CX-43, were also upregulated in the CES, proving that increasing vascular curvature promotes the invasion of tumor cells and intercellular communication with brain-resident cells." (PMID 38001146, 2023). "In prostate and pancreatic cancer, both HGF and MET genes are reported to be preferentially expressed in stem-like tumour cells." (PMID 37368660, 2023). "The concomitant exposure to hepatocyte growth factor (HGF)/c-MET inhibitors and sunitinib abrogated angiogenesis and tumor growth." (PMID 38148844, 2023). "Concurrent administration of sunitinib (VEGFR and PDGFR receptor tyrosine kinases inhibitor (RTKI)) and HGF/c-MET inhibitors effectively inhibited angiogenesis and tumor growth." (PMID 36959862, 2023). "Some of these TME-resident cells release hepatocyte growth factor (HGF) and promote the activation of c-Met, the receptor for HGF, within tumor cells." (PMID 38137344, 2023). "TANs have been shown to have tumor‐supportive capabilities such as (i) promoting tumor invasion, (ii) remodeling the extracellular matrix, (iii) secreting immunosuppressive cytokines and growth factors such as TGF‐β and hepatocyte growth factor, respectively." (PMID 38062888, 2023). "In mice bearing HGF-independent subcutaneous EBC-1 tumors with METamp, tepotinib (free base) 15 mg/kg QD led to tumor growth inhibition, with complete regressions in 7/10 animals, whereas 25 mg/kg QD led to complete regression in 10/10 mice." (PMID 36999986, 2023). "The anti-VEGF and anti-HGF motifs bind with high affinity and neutralize both VEGF-A and HGF, whereas the anti-HSA modules enhance MP0250 plasma half-life and tumor penetration potentiating the drug’s pharmacokinetic (, NCT03136653)." (PMID 37046651, 2023). "It is important to note that treatment of tumor cells with HGF resulted in an increase in phosphorylation of c-Met, PI3K, Akt, MEK, and ERK, whereas the inclusion of DA nullified the HGF-stimulated phosphorylation of these proteins." (PMID 37835375, 2023). "Heteronemin can effectively antagonize HGF/c-Met/STAT3 activation and tumor proliferation in refractory PCa cells." (PMID 36959792, 2023). "The HGF/c-MET pathway has been found to be aberrantly activated in a variety of tumors and plays a key role in various biological processes such as tumor occurrence, proliferation, metastasis, angiogenesis, and stemness." (PMID 37919751, 2023). "Taken together, we propose that increased expression of HGF in SNs following TRPV1 activation plays a role as a paracrine coordinator of the crosstalk between SNs and BC in the acidic tumor microenvironment in bone." (PMID 37461623, 2023). "Clinical pathological studies found high levels of cellular signal changes, e.g. HIF1α, HGF and TIMP-2, in the majority of primary tumours and their metastases." (PMID 35953652, 2023). "Induction of HGF and MET expression was observed in the progressing tumors and a cell line established from a TKI-resistant tumor exhibited acquired sensitivity to the MET inhibitor, crizotinib." (PMID 37470475, 2023). "Together with its ligand, hepatocyte growth factor (HGF), MET plays an important role in tumor proliferation, angiogenesis, and migration." (PMID 37296895, 2023). "Blocking HGF-MET signaling can simultaneously target primary TNBC tumorigenesis and lung metastasis in a three-dimensional organotypic tumor model and alleviate radioresistance." (PMID 37784082, 2023). "The mechanism behind this observation is that normal fibroblasts lacking TGFβR2 undergo myofibroblastic differentiation, recapitulating the tumor inductive activity of CAFs that secret various tumor-promoting factors, such as SDF1/CXCL12, FGF, HGF, and BMPs." (PMID 37254126, 2023).